C1QA (complement C1q A chain)
Description:
Core component of the complement C1 complex, a multiprotein complex that initiates the classical pathway of the complement system, a cascade of proteins that leads to phagocytosis and breakdown of pathogens and signaling that strengthens the adaptive immune system. The classical complement pathway is initiated by the C1Q subcomplex of the C1 complex, which specifically binds IgG or IgM immunoglobulins complexed with antigens, forming antigen-antibody complexes on the surface of pathogens: C1QA, together with C1QB and C1QC, specifically recognizes and binds the Fc regions of IgG or IgM via its C1q domain. Immunoglobulin-binding activates the proenzyme C1R, which cleaves C1S, initiating the proteolytic cascade of the complement system. The C1Q subcomplex is activated by a hexamer of IgG complexed with antigens, while it is activated by a pentameric IgM. The C1Q subcomplex also recognizes and binds phosphatidylserine exposed on the surface of cells undergoing programmed cell death, possibly promoting activation of the complement system.
Synonyms: C1QD1
Tractability: Small molecule: a structure with a bound ligand is known. Antibody: UniProt places it where antibodies can reach, with high confidence; its Gene Ontology location is reachable by antibodies, with high confidence; UniProt predicts a signal peptide or a membrane-spanning region.
Gene: Protein-coding gene on chromosome 1 (22,635,057 to 22,639,681, forward strand). Ensembl gene ENSG00000173372.
Subcellular location: Secreted; Cell surface
Pathways (Reactome):
Immune System: Classical antibody-mediated complement activation; Initial triggering of complement; Regulation of Complement cascade
Disease: Dengue virus activates/modulates innate and adaptive immune responses
Gene Ontology:
Molecular function: IgG binding; IgM binding; phosphatidylserine binding; protein binding; amyloid-beta binding
Biological process: complement activation, classical pathway; astrocyte activation; cell-cell signaling; complement activation; complement-mediated synapse pruning; microglial cell activation; neuron remodeling; synapse organization; synapse pruning; vertebrate eye-specific patterning
Cellular component: cell surface; complement component C1 complex; complement component C1q complex; extracellular matrix; extracellular region; symbiont cell surface; postsynapse; synapse; extrinsic component of postsynaptic membrane; extrinsic component of presynaptic membrane; glutamatergic synapse
Genetic constraint (gnomAD): Loss-of-function variants: 7 observed, 13.19 expected, observed/expected ratio (o/e) 0.53, 90% interval 0.3 to 1. The upper end of that interval is the gene's LOEUF score, 1, which puts it in group 4 of 6, group 1 being the genes least tolerant of losing a copy. Missense variants: 273 observed, 329.57 expected, observed/expected ratio (o/e) 0.83, 90% interval 0.75 to 0.92. Synonymous variants: 128 observed, 134.43 expected, observed/expected ratio (o/e) 0.95, 90% interval 0.82 to 1.1.
Gene-disease validity (ClinGen):
ClinGen rates the evidence that C1QA causes each of these diseases.
systemic lupus erythematosus related to C1QA (autosomal recessive): Definitive. Any systemic lupus erythematosus in which the cause of the disease is a variation in the C1QA gene.
Homologues: Orthologues: chimpanzee C1QA (99% identical), dog C1QA (80% identical), rabbit C1QA (76% identical), rat C1qa (73% identical), guinea pig C1QA (71% identical), mouse C1qa (71% identical), pig C1QA (71% identical), tropical clawed frog c1qa (48% identical), zebrafish c1qa (35% identical). Paralogues in human: C1QB (40% identical), C1QC (38% identical), C1QTNF7 (32% identical), C1QTNF9 (32% identical), C1QTNF2 (31% identical), C1QTNF9B (31% identical), COL8A2 (31% identical), C1QTNF5 (31% identical), COL10A1 (30% identical), COL8A1 (29% identical), OTOL1 (29% identical), ADIPOQ (28% identical), and 11 more.
Diseases named in the same sentence as C1QA in open-access papers:
C1QA is named in the same sentence as 142 diseases in open-access papers, as found by Europe PMC text mining. Sharing a sentence is not in itself a finding about the gene and the disease. The quoted sentences say what the papers report.
glaucoma (15 papers, 2013 to 2025). Increased pressure in the eyeball due to obstruction of the outflow of aqueous humor. "Inhibition of C1QA prevented synapse loss in aging mice and in mouse models of AD, Parkinson’s disease, and glaucoma." (PMID 32273396, 2020). "In the current datasets, optic nerve head monocyte-like cells highly express various complement genes (including C1qa, C1qb, C1qc, C3, and C3ar1), and complement activation is implicated in human glaucoma." (PMID 30670050, 2019). "The ablation of C1qa further prevented the progressive loss of retinal ganglion cells in a mouse model of glaucoma." (PMID 30126455, 2018). "Other studies on the pathological effects of C1qa in neurodegeneration have been implicated in mouse models of retinal ischemic injury, and glaucoma." (PMID 30126455, 2018). "In fact, we have previously shown that short-term IOP increase does not cause C1qa upregulation in the retina, making the cause of C1qa upregulation in glaucoma unclear." (PMID 26544197, 2015). "Genetic deletion of C1qa or pharmacological antagonism of complement component, C1, reduces dendritic degeneration during glaucoma." (PMID 34984584, 2022). "The classical pathway of the complement cascade is heavily implicated in glaucoma, and in DBA/2 J mice deficient in C1qa there is a significant decrease in retinal ganglion cell loss and optic nerve degeneration compared to regular DBA/2 J mice." (PMID 27048300, 2016). "Given that C1QA expression increases in the IPL early in glaucoma and that DBA/2 J mice deficient in C1qa are protected from optic nerve degeneration, we tested the role of C1qa in synapse degeneration in DBA/2 J glaucoma." (PMID 27048300, 2016). "This study demonstrates in two different animal models of glaucoma that early synaptic and dendritic atrophy is dependent on C1QA, a component of the C1 complex of the complement cascade." (PMID 27048300, 2016). "Further, in the DBA/2 J spontaneous glaucoma model, C1qa was identified to be differentially expressed in the retina and ONH preceding phenotypic glaucomatous damage." (PMID 27008854, 2016). "In summary, we present a detailed characterization of the effects of C1qa loss on RGC and axonal loss in a mouse model of glaucoma." (PMID 26544197, 2015). "Induction of C1qa in the CNS promotes synapse elimination and synaptic dysfunction during development, neurodegenerative diseases such as glaucoma and AD, and aging." (PMID 26512759, 2015). "Further, C1qa deficiency on the DBA/2J background prevented damage to the retina and optic nerve and protected mice from glaucoma." (PMID 24804771, 2014). "In early stages of glaucoma in this model, C1qa protein was re-expressed and localized to adult retinal synapses." (PMID 24804771, 2014). "Glaucomatous neurodegeneration was reduced in C1qa-deficient DBA/2J mice, indicating a crucial role of this protein and the complement cascade in general in glaucoma." (PMID 23806181, 2013). "Complement protein C1qa is expressed in optic nerve microglia, and genetic deletion of C1qa reduced RGC death and optic nerve degeneration and prevented loss of RGC dendrites in the DBA/2J mouse model of glaucoma." (PMID 39738875, 2025). "Taken together with the strong protective effect of C1qa knockout in retinal ganglion cell death and optic nerve damage, this suggests that inhibition of C1 should be considered as a therapeutic strategy for glaucoma." (PMID 27048300, 2016). "Furthermore, indicating an important role for the complement cascade in glaucoma, deletion of the complement component C1qa, protected ganglion cells from degeneration in a mouse model of glaucoma." (PMID 26637126, 2015). "Also, in a glaucoma mouse model, synaptic loss was absent in C1qa knock out mice, and treatment with a complement component 1 inhibitor reduced eye pathology." (PMID 28715462, 2017).
glaucoma (continued). "In the DBA/2 J model of spontaneous glaucoma, C1qa was among the earliest differentially regulated genes not only in the retina, but also at the optic nerve head (ONH) prior to onset of a glaucomatous phenotype." (PMID 27008854, 2016). "For instance, C1qa and C3 have been shown to be necessary for synaptic pruning in the retina during development, and may be necessary for RGC synapse remodeling early in glaucoma." (PMID 23806181, 2013).
melanoma (15 papers, 2015 to 2025). A malignant, usually aggressive tumor composed of atypical, neoplastic melanocytes. "(2016) reported retarded tumour growth and better survival in C1q-deficient (C1qa − / −) mice from an in vivo syngeneic B16 melanoma model." (PMID 41171372, 2025). "Cd74/C1q/Aif1-expressing macrophages also are characterized by higher expression of the complement components C1qa and C1qb, which have been positively correlated with immune cell infiltration, apoptosis, and improved survival in previous studies of melanoma." (PMID 41122966, 2025). "C1q-deficient mice lacking the C1qa gene exhibited reduced B16 melanoma tumor mass and vascular density, as well as prolonged survival." (PMID 40370471, 2025). "C1QA encodes the A-chain polypeptide of Complement C1q, which is a critical component of the TME, implying that C1QA could also be involved in melanoma." (PMID 35368886, 2022). "We also searched for metastatic melanoma cells in the lungs, the organ preferentially colonized by the cancer cells that escape from the primary tumour site, and detected metastases in 6 out of 11 WT mice but only in 1 out of 11 C1qa−/− mice." (PMID 26831747, 2016). "C1QA may affect melanoma progression and prognosis by regulating macrophages." (PMID 36059641, 2022). "And significant differences of C1QA and C1QB expressions were found in T stage, pathologic stage, melanoma ulceration, melanoma Clark level, and Breslow depth (P < 0.05)." (PMID 36443341, 2022). "Our findings will help reveal the multifaceted roles of C1QA, C1QB, and C1QC and provide evidence for future immunotherapy of melanoma." (PMID 36110204, 2022). "Compared to nevus and normal samples, significant higher expressions of GZMB, C1QA, and C1QB were observed in primary melanoma and metastatic melanoma in GSE46517." (PMID 36443341, 2022). "Within the immune system broadly, a large number of genes were identified with known roles in cancer, including AIM2, C1QA, and DFNA5 (also known as GSDME), which have been identified to have a mechanistic role in melanoma tumor growth." (PMID 35008167, 2021). "We focused on macrophages and identified TREM2+ TAMs specifically expressing TREM2, SPP1, APOE, C1QC, C1QB, and C1QA, which were significantly upregulated in melanomas not responsive to ICB therapy." (PMID 37187751, 2023).
prion disease (12 papers, 2019 to 2025). A transmissible disease that is caused by a protein that is able to induce abnormal folding of normal cellular proteins, leading to characteristic spongiform brain changes, which are associated with neuronal loss without an inflammatory response. "Mice deficient in C1qa complement protein and mice deficient in the Fc receptor gamma chain were partially or fully protected against spongiform encephalopathy upon exposure to limiting amounts of prions." (PMID 41018303, 2025). "Hartmann and colleagues showed that the abolishment of C3+ astrocytes in mice deficient in TNFα, interleukin‐1α and complement component C1qa coincided with accelerated CNS prion disease." (PMID 35852018, 2022). "This protective role for microglial C1qa and TNFα in prion disease in the CNS contrasts with the facilitative role observed for C1qa, C3, and TNFα in peripheral prion pathogenesis." (PMID 38786054, 2024). "This phenomenon appears to be unique to prion disease, as inhibition of C1qa and C3 has shown to be neuroprotective in animal models of other neurodegenerative diseases." (PMID 38786054, 2024). "Unexpectedly, elimination of three microglia-derived factors TNF-α, IL-1α and C1qa, which were thought to drive polarization of astrocytes into a neurotoxic state, accelerated the progression of prion diseases." (PMID 33980286, 2021). "Although the deposition of misfolded PrPSc was unchanged, we found that knockout of TNF-α, IL-1α and C1qa with the abolishment of C3+-astrocyte formation let to a significant acceleration of the prion disease course." (PMID 31118110, 2019). "Surprisingly, abolishment of C3+-astrocyte formation by knocking out TNF-α, IL-1α and C1qa accelerated the prion disease course." (PMID 31118110, 2019). "Of note, TNF-α, IL-1α and C1qa are upregulated in mouse models of prion disease and TNF-α and IL-1α in human CJD, which would make polarization of astrocytes towards A1 very likely in prion diseases." (PMID 31118110, 2019). "Five genes from the HIP negative correlates associated with the Prion disease pathway:C1QA,C7,C1QB,C6 andC1QC; these are all related to the complement pathway of the innate immune system." (PMID 31448102, 2019). "We then investigated the impact of these astrocytes on prion disease pathophysiology by prion infecting mice with a knockout of the three cytokines TNF-α, IL-1α and C1qa, which are unable to develop A1-astrocytes upon stimulation." (PMID 31118110, 2019). "C1QA, NCAM2 and PSMA7 were enriched in the prion disease pathway." (PMID 36277688, 2022). "Recently, the influence of microglia-induced A1-reactive astrocytes during prion disease was assessed by infecting triple knockout mice lacking Tnf, IL-1a, and C1qa with prions." (PMID 32381108, 2020). "Knockout or depletion of either TNF-α or C1qa in mouse models of prion disease did not influence prion disease course after intracerebral prion infection, however, microglia homeostatic phenotypes had not been determined in these studies." (PMID 31118110, 2019). "Therefore, it would be interesting to determine, if C3aR is altered in prion diseases and could pose a more suitable target than the cytokine triad TNF-α, IL-1α and C1qa." (PMID 31118110, 2019). "To investigate their impact on prion disease pathophysiology and to evaluate their potential therapeutic targeting, we infected TNF-α, IL-1α, and C1qa Triple-KO mice (TKO-mice), which do not transit astrocytes into A1, with prions." (PMID 31118110, 2019). "Therefore, we intra-cerebrally infected Triple-KO mice (TKO) lacking expression of TNF-α, IL-1α and C1qa (which fail to develop A1 reactive astrocytes following inflammatory insult) with RML-prions and determined pathophysiology of prion disease progression in comparison to infected WT-mice (WT)." (PMID 31118110, 2019).
breast carcinoma (11 papers, 2007 to 2022). "Previous studies have found that complement C1qA chain (C1QA) is associated with distant metastasis of breast cancer." (PMID 35185791, 2022). "The results in complement-deficient mice were unexpected, as we have previously demonstrated that C1qA and C3 deficiencies are associated with increased Her2 expression and aggressiveness of autochthonous mammary cancers in neuT mice." (PMID 35203439, 2022). "Bandini also confirmed that C1qA, C1qB and C1qC expression levels were positively linked to a good prognosis in breast cancer patients using in vivo investigation of C1q-deficient mice." (PMID 34079754, 2021). "A polymorphism associated with C1qA decreases complement activity, thereby reducing the hematogenous spread of breast cancer." (PMID 34257539, 2021). "In contrast, single nucleotide polymorphism in the C1qA component of complement correlates with the pattern of clinical breast cancer metastasis." (PMID 19484134, 2009). "Specifically, C1QA, which is a gene involved in the classical complement pathway, was recently shown to harbor a single nucleotide polymorphism that correlated with distant metastasis in breast cancer." (PMID 17683518, 2007). "One study revealed that increased C1QA expression was significantly related to a better prognosis in breast cancer." (PMID 36059641, 2022). "Recently, we showed that overexpression of C1QA in ER-negative basal-like breast cancer patients, which have the poorest prognosis, is associated with better outcome." (PMID 20332777, 2010). "An earlier onset of spontaneous Her2+ mammary cancers and lung metastases, paralleled by reduced mouse survival, was observed in neuT females lacking C1qA (neuT-C1KO) or C3 (neuT-C3KO) complement components." (PMID 35203439, 2022).
COVID-19 (10 papers, 2020 to 2025). A disease caused by infection with severe acute respiratory syndrome coronavirus 2. "The identification of key immune-modulating genes like ISG15, SERPING1, C1QA, C1QB, and VSIG4 opens avenues for therapeutic approaches that aim to modulate the immune response and improve outcomes in severe COVID-19 cases via upregulation of expression of these genes." (PMID 40374692, 2025). "Similarly, in previous reports, FGB, FGG, complements C4, C3, C5, C2, C9, and complement C1q subcomponent subunits A, B, and C (C1QA, C1QB and C1QC) were found to be upregulated in the lung tissues of patient with COVID-19." (PMID 38882332, 2024). "Clusters A to C contain proteins with lower levels in COVID-19 convalescents, e.g. proteins functioning in cell adhesion and platelet degranulation (e.g. fibrinogen A (FGA), VWF), and innate immunity/the complement system (e.g. C1R, C1S, C1QA, C1QC, and GGH)." (PMID 38396092, 2024). "Based on our data and previous research, increased expression of C1QA and C1QB could to be involved in pathogenesis and lethality of COVID-19, and could be considered a molecular marker of milder cases, and stimulation of their expression could be a possible option for therapeutic intervention." (PMID 40374692, 2025). "Of note, the complement genes C1QA and C1QB that show elevated expression in nonclassical monocytes from COVID-19 patients are preferentially expressed in BA.2 patients." (PMID 35441161, 2022).
osteosarcoma (9 papers, 2021 to 2024). A usually aggressive malignant bone-forming mesenchymal neoplasm, predominantly affecting adolescents and young adults. "C1qA is associated with angiogenesis, innate immune response, osteosarcoma (OS), schizophrenia, hypertension, aging, and obesity." (PMID 36845383, 2023). "The prognostic biomarkers C1QA, CD74, and HLA-DMA for pediatric metastatic osteosarcoma were identified using RNA-sequencing data (level 3) associated with clinical information from the TARGET-osteosarcoma dataset." (PMID 38256356, 2024). "Thus, C1QA and C1QB may be implicated in the pathogenesis and metastasis of osteosarcoma, and the underlying mechanisms may rely on regulating macrophage polarization in osteosarcoma." (PMID 38256356, 2024). "A Cox regression analysis and KM survival analysis were performed to screen survival-related central DEGs based on the osteosarcoma project of the TARGET database, and three survival-related central DEGs were identified (C1QA, CD74, HLA-DMA)." (PMID 38256356, 2024). "In a recent analysis, complement classical pathway genes C1QA, C1QB, C1QC were proved to be protective factors for survival in osteosarcoma." (PMID 35493104, 2022). "The differential expressions of C1QA, C1QB and C1QC were found to be closely related to the survival prognosis, pathological features, and tumor microenvironment of osteosarcoma, which can help improve the clinical prognosis and immunotherapy." (PMID 35765947, 2022). "C1QA and C1QB might be potential prognostic factors and indices of tumor microenvironment remodeling in osteosarcoma." (PMID 36247009, 2022). "The present study delves into the intricate roles of C1QA, CD74, and HLA-DMA, exploring their interactions within the tumor microenvironment and their implications for the immunotherapy response, thereby providing new insights into the treatment of pediatric osteosarcoma." (PMID 38256356, 2024). "However, the immunomodulatory mechanism and actions of C1qA, C1qB and C1qC in osteosarcoma are not clear." (PMID 34079754, 2021).